EGFR (epidermal growth factor receptor)
Diseases named in the same sentence as EGFR in open-access papers (continued):
Sharing a sentence is not in itself a finding about the gene and the disease.
non-small cell lung carcinoma (continued). "In EGFR-driven non-small-cell lung cancer, erlotinib and gefitinib are used to target constitutively active EGFR with mutationally altered active sites." (PMID 38396993, 2024). "The 11 currently reportable or actionable variants for non-small cell lung cancer (NSCLC) were extensively verified (n=126) (ALK, EGFR, BRAF, KRAS, NTRK 1/2/3, ROS, RET, MET, ERBB2)." (PMID 36522176, 2024). "EGFR is an important target protein for targeted therapy in cancer, especially non-small cell lung cancer." (PMID 39777265, 2024). "This study examined the potential of combining LJF with EGFR TKIs in the treatment of non-small cell lung cancer, particularly focusing on LJF as an auxiliary agent to mitigate adverse effects." (PMID 39314630, 2024). "Numerous malignancies, including those of the breast, ovary, colon, and non-small cell lung cancers (NSCLC), are linked to overexpression of EGFR." (PMID 38398626, 2024). "Osimertinib has demonstrated efficacy in patients with epidermal growth factor receptor (EGFR) T790M-positive non-small cell lung cancer (NSCLC) in clinical trials." (PMID 38753697, 2024). "Osimertinib is a third-generation tyrosine kinase inhibitor clinically approved for first-line treatment of EGFR-mutant non-small cell lung cancer (NSCLC) patients." (PMID 38177190, 2024). "For example, in 2024, Han Zhang and his coworkers designed and synthesized novel 4-phenoxyquinazoline compounds as dual EGFR/c-Met suppressors to treat non-small cell lung cancer." (PMID 38398626, 2024). "Within each tumor type, the risk of brain metastasis is related to disease status and molecular subtype (i.e., EGFR-mutant non-small cell lung cancer, HER2-positive and triple-negative breast cancer, BRAF and NRAF-mutant melanoma)." (PMID 38893253, 2024). "Circulating tumor DNA (ctDNA) offers a new paradigm in optimizing treatment strategies for epidermal growth factor receptor (EGFR) mutant non-small cell lung cancer (NSCLC)." (PMID 38473302, 2024). "AURKB inhibition reduced phospho-histone H3 to attenuate acquired resistance to anti-EGFR therapy in non-small cell lung cancer." (PMID 38713155, 2024). "Therein, afatinib, a drug for non-small cell lung cancer, achieved its therapeutic goal through potent, irreversible dual inhibition of EGFR and HER2 tyrosine kinases." (PMID 39039366, 2024). "According to the literature, increased EGF expression was observed in 70–75% of established CRC cases, and EGFR was associated with various types of cancer, including CRC, breast cancer, and non-small cell lung cancer." (PMID 39063041, 2024). "For instance, TGFB2 induced epithelial-mesenchymal transition and activated the NF-κB pathway to contribute to osimertinib resistance in epidermal growth factor receptor (EGFR) mutant non-small cell lung cancer." (PMID 38914663, 2024). "For this reason, targeted treatment options against EGFR have been developed and are clinically used currently, especially in cases of non-small cell lung cancer (NSCLC), the most common type of lung cancer." (PMID 39339249, 2024). "Using single cell cloning and expansion techniques, we established monoclonal cell subpopulations (MCPs) from a commercially available epidermal growth factor receptor (EGFR)-mutant non-small cell lung cancer cell line." (PMID 39061010, 2024). "For instance, in non-small cell lung cancer (NSCLC), the presence of EGFR mutations or ALK rearrangements has successfully guided the use of targeted therapies, dramatically improving outcomes." (PMID 39512765, 2024). "Some new compounds, such as CLN-081 and DZD9008 also have shown auspicious activity, but platinum-based chemotherapy is still the primary first-line treatment for EGFR 20 insertion non-small cell lung cancer." (PMID 38567147, 2024).
non-small cell lung carcinoma (continued). "The dramatic improvement in the prognosis of patients with advanced epidermal growth factor receptor (EGFR)-mutant non-small cell lung cancer (NSCLC) became possible thanks to the advent of EGFR-tyrosine kinase inhibitors (EGFR-TKIs)." (PMID 38611009, 2024). "Osimertinib is a third-generation EGFR-TKI, specifically targeting EGFR-activating mutations and the EGFR T790M mutation in advanced non-small cell lung cancer (NSCLC)." (PMID 38610654, 2024). "The hsa-miR-133b significantly inhibits cell proliferation in non-small cell lung cancer (NSCLC) by directly targeting the epidermal growth factor receptor (EGFR) and disrupting its downstream signaling pathways." (PMID 39701957, 2024). "Insertion mutations in exon 20 of the epidermal growth factor receptor gene (EGFR exon20ins) are rare, heterogeneous alterations observed in non-small cell lung cancer (NSCLC)." (PMID 38844820, 2024). "This has been observed in non-small cell lung cancer (NSCLC) for EGFR targeting drugs, where 50% of patients treated with erlotinib and gefitinib develop a threonine-to-methionine mutation (T790M) within one year." (PMID 39280248, 2024). "Currently, third-generation drugs targeting the EGFR are predominantly employed in the treatment of non-small cell lung cancer (NSCLC)." (PMID 38751788, 2024). "Non-small cell lung cancer with abundant expression of wild-type EGFR is intrinsically resistant to EGFR tyrosine kinase inhibitors, such as afatinib." (PMID 39497143, 2024). "Rociletinib, an epidermal growth factor receptor (EGFR) tyrosine kinase inhibitor widely used for non-small cell lung cancer patients, was highly abundant in 7 cancers especially in LIHC49." (PMID 38245572, 2024). "Based on our findings, osimertinib, a potent EGFR inhibitor used for the treatment of patients with metastatic non-small cell lung cancer, significantly reduced the efficacy of SARS-CoV-2 infection." (PMID 39291996, 2024). "Both TKIs reversibly bind EGFR and are used for the treatment of locally advanced or metastatic non-small cell lung cancer." (PMID 38965505, 2024). "This study focused on patients with advanced EGFR-mutated non-small cell lung cancer and employed a cancer organoid-based diagnosis reactivity prediction (CODRP)-based precision oncology platform to assess the efficacy of EGFR inhibitor treatments." (PMID 38773241, 2024). "Advanced epidermal growth factor receptor (EGFR)-mutant non-small cell lung cancer (NSCLC) patients who received afatinib as first-line therapy between April 2018 and June 2022 were included, and patient medical records were reviewed." (PMID 38317094, 2024). "Studies have demonstrated that overexpression of TIP30 can restore the sensitivity of non-small cell lung cancer cells to gefitinib by attenuating both cytoplasmic and nuclear EGFR signaling pathways." (PMID 39404930, 2024). "Osimertinib has a higher efficacy in treating EGFR-mutant non-small-cell lung cancer than traditional platinum therapy and showed promising increases in progression-free survival." (PMID 38396993, 2024). "The management of non-small cell lung cancer (NSCLC) has evolved significantly with a focus on identifying driver mutations, such as EGFR and ALK-EML4, within tumor samples to guide personalized treatment strategies." (PMID 38494473, 2024). "Generalizability was further assessed on a cohort of non-small cell lung cancer patients who received the EGFR inhibitor osimertinib (215 patients)." (PMID 38940147, 2024). "Human epithelial growth factor receptor 2 (HER2) amplification is an important mechanism of acquired resistance to anti-epidermal growth factor receptor (EGFR) therapy in non-small cell lung cancer (NSCLC) patients." (PMID 39184039, 2024). "Dacomitinib is an irreversible epidermal growth factor receptor (EGFR) tyrosine kinase inhibitor indicated for the treatment of patients with advanced non-small-cell lung cancer (NSCLC) and EGFR-activating mutations." (PMID 38258127, 2024).
non-small cell lung carcinoma (continued). "The development of acquired resistance to small molecule tyrosine kinase inhibitors (TKIs) targeting epidermal growth factor receptor (EGFR) signaling has hindered their efficacy in treating non-small cell lung cancer (NSCLC) patients." (PMID 38397056, 2024). "A3B expression in EGFR mutant (EGFRmut) non-small-cell lung cancer (NSCLC) mouse models constrained tumorigenesis, while A3B expression in tumors treated with EGFR-targeted cancer therapy was associated with treatment resistance." (PMID 38049664, 2024). "The clinical trial results indicate that gefitinib belongs to the first generation of targeted therapeutic drugs, which can bind to the epidermal growth factor receptor, and has a good therapeutic effect on non-small cell lung cancer, breast cancer, etc6." (PMID 38649732, 2024). "EGFR is widely expressed in non-small-cell lung cancer (NSCLC) cell lines and can be used as a target for immunotherapy in these cancers." (PMID 38919533, 2024). "This study explored the potential benefits of combining first-generation epidermal growth factor receptor (EGFR)-tyrosine kinase inhibitor with chemotherapy as a neoadjuvant treatment for patients with stage III N2 EGFR-mutant non-small cell lung cancer." (PMID 38529688, 2024). "Further emphasizing targeted approaches, docetaxel and resveratrol were encapsulated in epidermal growth factor receptor-targeted lipid–polymer hybrid nanoparticles (EGF DTX/RSV LPNs) designed for the targeted treatment of non-small cell lung cancer (NSCLC)." (PMID 38794306, 2024). "Non-small-cell lung cancers have developed more precise treatment options based on molecular markers, like EGFR." (PMID 38396993, 2024). "PROTAC targeting epidermal growth factor receptor (EGFR) has been used to study tumor cells such as non-small cell lung cancer." (PMID 38664743, 2024). "Almost all non-small cell lung cancer (NSCLC) patients initially responding to EGFR tyrosine kinase inhibitors (TKIs) develop acquired resistance." (PMID 38177097, 2024). "Osimertinib has become standard care for epidermal growth factor receptor (EGFR)-positive non-small cell lung cancer (NSCLC) patients whereas drug resistance remains inevitable." (PMID 38658988, 2024). "In non-small-cell lung cancer (NSCLC), specific CAF subsets have been linked to EGFR-TKI resistance." (PMID 38392348, 2024). "Digital PCR has proven to be a valuable technique to detect EGFR and Kirsten rat sarcoma virus (KRAS) gene mutations in CTCs from non-small-cell lung cancer patients, demonstrating its potential as a liquid biopsy for monitoring treatment response." (PMID 38398206, 2024). "Erlotinib is an epidermal growth factor receptor (EGFR) inhibitor that is approved by the FDA to treat non-small cell lung cancer (NSCLC)." (PMID 39434878, 2024). "EGFR-targeting tyrosine kinase inhibitors (TKIs) have been commonly used to target and treat EGFR-positive non-small cell lung carcinoma (NSCLC) with differential sensitivity of TKIs to different EGFR mutations." (PMID 39057170, 2024). "The discovery of the first driver gene, the epidermal growth factor receptor (EGFR), has ushered in the era of personalized and precise medical treatment for non-small cell lung cancer (NSCLC)." (PMID 38440180, 2024). "In non-small cell carcinoma A549 cells, β1-integrin silencing inhibits EGFR-dependent cell proliferation even in the presence of serum, further indicating that integrins are required for cell proliferation." (PMID 39594667, 2024). "Protein tyrosine kinase 2 (PTK2), epidermal growth factor receptor (EGFR), and toll-like receptor (TLRs) are amplified in non-small cell lung cancer (NSCLC)." (PMID 38816856, 2024). "Non-small cell lung cancer (NSCLC) with EGFR T790M is moderately responsive to first- and second-generation EGFR tyrosine kinase inhibitor." (PMID 38699639, 2024).
non-small cell lung carcinoma (continued). "Of all the patients, 25 had non-small cell lung cancer (NSCLC) and 10 had epidermal growth factor receptor (EGFR) or Anaplastic Lymphoma Kinase (ALK) mutations." (PMID 39060968, 2024). "Epidermal growth factor receptor (EGFR) inhibitors have been used in clinical for the treatment of non-small-cell lung cancer for years." (PMID 38339163, 2024). "Notable examples include drugs like imatinib (Gleevec), which targets the BCR-ABL fusion protein in chronic myeloid leukemia (CML), and erlotinib (Tarceva), acts on the epidermal growth factor receptor (EGFR) in non-small cell lung cancer (NSCLC)." (PMID 39001539, 2024). "EGFR has been shown to be constitutively activated in cells of various epithelial tumors such as in non-small-cell lung cancer, colorectal cancer, and head and neck tumors." (PMID 39772250, 2024). "EGFR tyrosine kinase inhibitors (TKIs), for instance, have demonstrated clinical success in non-small cell lung cancer and show potent anti-proliferative effects on HCC cells." (PMID 39319846, 2024). "Among these, epidermal growth factor receptor (EGFR) tyrosine kinase inhibitors (TKIs) are the most widely used in targeted therapy for non-small-cell lung cancer (NSCLC)." (PMID 39518531, 2024). "The combination of API with oxaliplatin exerts a significant impact on non-small cell lung cancer (NSCLC) by modulating the EGFR and its downstream signaling pathways." (PMID 39605916, 2024). "EGFR serves as the primary driver in non-small-cell lung cancer (NSCLC) and is a promising therapeutic target for NSCLC." (PMID 38399447, 2024). "Lazertinib is a recently developed third-generation epidermal growth factor receptor (EGFR)-tyrosine kinase inhibitors used for patients with advanced EGFR T790M-positive non-small-cell lung cancer." (PMID 38918528, 2024). "The E3 ubiquitinases Cbl-b and c-Cbl were shown to be involved in the downregulation of PD-L1 in EGFR wild-type non-small cell lung cancer (NSCLC)." (PMID 38654302, 2024). "ANXA8 regulates the proliferation of human non-small cell lung cancer cells A549 through the EGFR-AKT-mTOR signaling pathway." (PMID 38952985, 2024). "Similar to first-generation TKIs, afatinib showed strong results in treating EGFR-driven brain metastasis of non-small-cell lung cancer." (PMID 38396993, 2024). "In 2021, a multi-channel and multi-task DL model proposed by Dong was used to predict EGFR and KRAS mutations in non-small cell lung cancer, with a prediction accuracy of about 70%." (PMID 38965599, 2024). "Afatinib improved outcomes and tolerability compared to gefitinib in patients with EGFR-driven non-small-cell lung cancer." (PMID 38396993, 2024). "Noteworthy examples include imatinib, which inhibits the BCR/ABL tyrosine kinase in chronic myeloid leukemia (CML), and gefitinib, targeting the epidermal growth factor receptor (EGFR) in non-small-cell lung cancer (NSCLC)." (PMID 38920700, 2024). "ART promotes anti-tumor immunity and overcomes EGFR-TKI resistance in non-small-cell lung cancer by enhancing oncogenic TAZ degradation." (PMID 39525639, 2024). "In the current treatment landscape for non-small cell lung cancers, epidermal growth factor receptor-tyrosine kinase inhibitors have emerged as a well-established treatment option for patients with advanced or metastatic disease." (PMID 38494473, 2024). "Osimertinib is an irreversible EGFR tyrosine kinase inhibitor (TKI) approved for non-small cell lung cancer treatment." (PMID 38605419, 2024). "The interaction between MET and EGFR is particularly important in non-small-cell lung carcinoma (NSCLC)." (PMID 38675409, 2024). "For brain metastases (BMs) from EGFR/ALK-positive non-small cell lung cancer (NSCLC), the best time to administer tyrosine kinase inhibitors (TKIs) and brain radiotherapy (RT) has not been identified." (PMID 38262977, 2024).
non-small cell lung carcinoma (continued). "In conclusion, the analysis of circulating tumor DNA (ctDNA) in EGFR-mutant non-small cell lung cancer plays a critical role in various facets of patient management." (PMID 38473302, 2024). "Amivantamab is an EGFR antibody that works on the receptors’ extracellular domain and was found to be successful in non-small-cell lung cancer." (PMID 38396993, 2024). "This is the case for EGFR-mutant or ALK-rearranged non-small cell lung cancer inhibitors, tucatinib and trastuzumab–deruxtecan for HER2-positive breast cancer and BRAF inhibitors for melanoma." (PMID 38893253, 2024). "EGFR serves as a transmembrane receptor primarily situated on the cell surface and is frequently overexpressed in patients with non-small cell lung cancer (NSCLC), thereby facilitating tumor cell proliferation and metastasis." (PMID 38980474, 2024). "Small-cell lung cancer (SCLC) transformation has been considered to be the most common phenotypic change in EGFR-mutant non-small-cell lung cancers (NSCLCs) during disease progression under treatment with earlier-generation EGFR TKIs." (PMID 39456595, 2024). "Genetic characterization of oncogenic driver mutations (EGFR, KRAS, ALK, ROS) has transformed the management of non-small cell lung cancer (NSCLC) therapy with the introduction of molecularly targeted therapies, allowing an individualized treatment approach." (PMID 38643157, 2024). "The epidermal growth factor receptor (EGFR) is a common driver of non-small cell lung cancer (NSCLC)." (PMID 38338651, 2024). "In the present study, we identified ten patients with early stage, resectable, non-small cell lung cancer who presented with multiple, anatomically distinct, EGFR-mutant tumors." (PMID 39406916, 2024). "According to the 2020 CSCO guidelines for non-small-cell lung cancer, the first-line treatment for LUAD with EGFR exon 20 mutation is chemotherapy plus bevacizumab." (PMID 39743996, 2024). "In this research, P6-SN38 was prepared and subsequently assessed in vitro and in vivo for treating EGFR overexpressed non-small cell lung cancer." (PMID 39771591, 2024). "Gefitinib has yielded clinically positive responses in patients with advanced and metastatic non-small-cell lung cancer (NSCLC) with hyperactive and mutated EGFR genes, primarily in exon 19 (del 19) or exon 21 (L858R) regions." (PMID 38790220, 2024). "In locally advanced or metastatic non-small cell lung cancer, EGFR tyrosine kinase inhibitor (TKI) treatment is the recommended first-line therapy with confirmed actionable EGFR mutations." (PMID 38605928, 2024). "Although third-generation Epidermal growth factor receptor—tyrosine kinase inhibitors (EGFR-TKI) is standard of care for patients with EGFR-mutant Non-small cell lung cancer (NSCLC), little is known about the predictors of response or resistance." (PMID 39638994, 2024). "In studies of EGFR, although considerable advancements have been made in non-small cell lung cancer, little is known about it in HCC." (PMID 39338323, 2024). "To develop a model to study a saturated library of mutated EGFR proteins in a physiologically context, we validated the use of PC9 cells, a non-small cell lung cancer (NSCLC) cell line, which contains an endogenous EGFR exon 19 deletion." (PMID 38548752, 2024). "Of note, MET amplification often represents a mechanism to sustain secondary resistances to epidermal growth factor receptor (EGFR) targeting agents in Non-Small-Cell Lung Cancer (NSCLC) and colorectal cancer (CRC)." (PMID 38892318, 2024). "Aberrant activation of mesenchymal epithelial transition (MET) has been considered to mediate primary and acquired resistance to epidermal growth factor receptor (EGFR) tyrosine kinase inhibitors (TKIs) in EGFR-mutant non-small cell lung cancer (NSCLC)." (PMID 39354638, 2024).